CD4 (CD4 molecule)
Diseases named in the same sentence as CD4 in open-access papers (continued):
Sharing a sentence is not in itself a finding about the gene and the disease.
lupus (continued). "Whether the delivery of IL-2 and TGF-β, which are deficient in SLE, mediated by nanoparticles (NPs) to mouse CD2+ and CD4+ cells, could induce a tolerogenic immune response and then protect mice from a lupus-like disorder was investigated." (PMID 35116040, 2021). "For example, miR-155, a key player for B cell development and function, was increased in human lupus whole peripheral blood, PBMCs, and CD19+ B cells, and also in the CD4+ T and CD19+ B cells from murine lupus-prone MRL-lpr mice." (PMID 34062726, 2021). "Although CD4+CD25+FOXP3+ Treg population was depleted, CD25 was upregulated on lupus CD4+ T cells, resulting in diminished proportion of CD4+CD25+FOXP3+ Treg cells among the CD4+CD25+ cells in SLE." (PMID 33763079, 2021). "ZBTB33 binds to a motif in the Ctse locus in a methylation-dependent manner, and subsequently represses the expression of Cathepsin E and IL-10 in murine thymoma EL-4 cells, and in CD4+ T cells of MRL/lpr mice or patients with systemic lupus erythematosus (SLE)." (PMID 34349770, 2021). "In human peripheral blood CD4 and CD8 T cells, basal levels of UBA6 in lupus patients presented much lower than those in healthy controls." (PMID 35011668, 2021). "LAT-1 deletion or inhibition blocks the expansion of IL-17 secreting γδ and CD4+ T cells in both human cells and imiquimod (a TLR7 agonist)-induced lupus and psoriasis-like animal models." (PMID 33692797, 2021). "In support of this idea, we found that lupus-established sanroque mice overexpress GM-CSF, IL-6, and IFN-γ in their spleens, and CD4+ T cells are in part responsible for their production." (PMID 33643317, 2021). "As indicated from the results, circ_0012919 reduction enriched the expression of DNMT1, decreased the expressions of CD70 and CD11a, and reversed the DNA hypomethylation of CD11a and CD70 in CD4+ T cells of systemic lupus erythematosus (SLE); however, it was reversible by DNMT1 reduction." (PMID 32665846, 2020). "Therefore, we sought to explore the relationship between ac4C modification and SLE by performing epitranscriptome ac4C-modified profiles of lupus CD4+ T cells." (PMID 32984334, 2020). "Suppression of EZH2 expression in CD4+ T cells might be mediating at least some of the therapeutic effects observed with blocking mTOR activation and with glycolysis inhibitors in SLE and lupus-prone animal models." (PMID 32395334, 2020). "Both CD4+ and CD8+ T cells contributed to the overproduction of inflammatory cytokine IFNγ in human lupus patients." (PMID 32646370, 2020). "Apigenin suppresses IFN-γ and IL-17 responses in T cells from a lupus-prone mouse model and decreases cyclooxygenase-2 (COX-2) levels in lupus CD4+ T cells, B cells, dendritic cells, and macrophages, resulting in delayed disease progression." (PMID 33333788, 2020). "Forced overexpression of PDP2 reduced Th17 differentiation in CD4 T cells from both SLE patients and lupus-prone mice." (PMID 32477606, 2020). "CD4+ T cells are also important for pathological processes of autoimmune diseases, such as systemic lupus erythematosus (SLE), autoimmune type 1 diabetes (T1D), multiple sclerosis (MS), rheumatoid arthritis (RA), inflammatory bowel disease (IBD), and allergic responses or atopic diseases." (PMID 32377533, 2020). "In the current study, we demonstrated that IL-Y aggravated the progression of cGVHD by activating T and B cells, and increasing TNF-α secretion by CD4+ and CD8+ T cells in scleroderma-like and lupus-like cGVHD models." (PMID 33329519, 2020). "Metformin has a therapeutic effect, confirmed in an animal model of systemic lupus erythematosus (SLE) through mechanisms involving the inhibition of oxidative phosphorylation (OXPHOS) and the diminishment of CD4+ T cell activation." (PMID 32825027, 2020). "miR-21 is upregulated in both PBMCs or CD4+T cells from SLE patients and splenic CD4+ T cells from lupus-prone mice." (PMID 32308657, 2020).
lupus (continued). "In contrast to mTORC2, increased activation of mTORC1 is observed in CD4+ T cells obtained from SLE patients and lupus prone mice leading to elevated IL-17, IL-4 producing double negative T cell expansion and regulatory T cell (Treg) depletion." (PMID 32257420, 2020). "In our studies, we analyzed and compared the expression of EGR2 in resting and activated CD4+ T, CD8+ T, B cells of lupus and control mice." (PMID 32646370, 2020). "In systemic lupus erythematosus, with characteristic of overactive T cells and over-stimulated B cells, hematopoietic progenitor kinase 1 (HPK1) expression was decreased in CD4+ T cells." (PMID 31701394, 2019). "Its expression on T cells was proven to correlate with lupus activity either when analyzed on CD3+ T cells, CD4+ T cells, or CD8+ T cells." (PMID 31824514, 2019). "In lupus-prone mice and SLE patients, CD4+ T cells present an enhanced cellular metabolism." (PMID 31057554, 2019). "HPK1 mRNA and protein levels were observed to be significantly decreased in CD4+ T cells of patients with systemic lupus erythematosus (SLE), contributing to the overactivation of T and B cells in SLE, supporting an important role of HPK1 in the maintenance of peripheral tolerance." (PMID 30913212, 2019). "SLE patients also showed the similar tendency with MRL mice; the expression level of Ctse and IL10 mRNAs in CD4+ T cells is upregulated in lupus patients than healthy control, while PDCD4 mRNA lower tendency in lupus patients than healthy control." (PMID 30816218, 2019). "Furthermore, estrogens stimulate calcineurin expression which enhances expression of the X-linked gene product CD40L on lupus CD4+ T cells, resulting in their strengthened crosstalk with CD40-expressing B cells and autoantibody production in SLE patients." (PMID 31575058, 2019). "To determine the effect of SH3BP2 on T cells, we examined T cell subsets in lymph nodes from lupus-prone mice and found the ratios of CD4+ T cells, CD8+ T cells, and CD4+CD25+ T cells to be comparable between Faslpr/lpr and Sh3bp2KI/+Faslpr/lpr mice." (PMID 31052273, 2019). "Increased glycolysis has been noted in CD4+ T cells from individuals with SLE and in mouse models of lupus, and furthermore, treatment of this abnormally enhanced glycolysis in mice resulted in a shift of immunophenotype toward that of healthy controls." (PMID 29740453, 2018). "By contrast, a recent work carried out on Systemic lupus erythematosus and SSc patients by Janahi and collaborators provides data supporting higher prevalence of HCMV-specific CD4+ than CD8+ T cell responses." (PMID 30231575, 2018). "Lupus-prone mice and SLE patients have been found to exhibit activated metabolism of CD4+ T cells; the use of metabolic inhibitors was found to effectively normalize these features and was associated with therapeutic effects." (PMID 30577810, 2018). "Further, we showed that TGF-β3 ameliorated lupus pathologies with suppressing TFH cells and antibody-producing cells while maintaining total CD4+ T cells and B220+ B cell count in IL-10-sufficient MRL/lpr mice." (PMID 29963056, 2018). "PBMC from women with inactive and active lupus and inactive and active SS were isolated and stained with fluorochrome conjugated antibodies to CD3, CD4, CD28, CD70, CD40L and the KIR gene family then analyzed by multicolor flow cytometry." (PMID 28620656, 2017). "In accordance with the changes in thymic B cells, the percentages and the absolute numbers of thymic CD4+CD8- and CD4-CD8+T cell also increased in lupus-prone mice." (PMID 29163765, 2017). "Recently, a subset of FOXP3+ CD4+ T cells with low expression of CD25 was reported to be increased in peripheral blood of autoimmune systemic lupus erythematosus (SLE) patients, a finding that was later expanded to the peripheral blood of multiple sclerosis and rheumatoid arthritis patients." (PMID 28747257, 2017).
lupus (continued). "Lymphocytes from the lymph nodes of 7-9-week-old non-lupus-prone MRL/+ and lupus-prone MRL/lpr mice were stained with anti-mouse CD3, CD4, CD8, and RORγt antibodies, and analyzed by FACS." (PMID 29163765, 2017). "In this study, SLE patient samples and the B6.MRL/lpr lupus mouse model were both found to have an association between the significantly decreased Treg cell frequency and marked expansion in the NKG2D+CD4+ T cell population." (PMID 28455530, 2017). "This was somewhat unexpected, as NKG2DL induction among lupus B cells would be consistent with NKG2D-mediated co-stimulation driving proliferative expansions of autoreactive and B cell antigen-specific NKG2D+CD4 T cell populations." (PMID 28944101, 2017). "In addition, hypermethylation of 11 CpGs sites within RNF39 was seen in naïve CD4+ T cells of patients with systemic lupus erythematosus (SLE) who had a history of discoid rash." (PMID 28729889, 2017). "In accordance with the data in lupus-prone mice, lupus-inducing pristane up-regulated the thymic CD4+CD8- and CD4-CD8+T cell percentage and absolute numbers and reduced CD4+CD8+T cells." (PMID 29163765, 2017). "In lupus MRL/lpr mice, activated CD4+ T cells secrete 10 times more IL-21 than control mice and IL-21R deficiency leads to reduced numbers of TFH cells." (PMID 27635407, 2016). "PP5 was found to be overexpressed in CD4+CD28+ T cells treated with H2O2 and ONOO− and in T cells from lupus patients." (PMID 28239687, 2016). "We proved that CD4+CD25+Treg cells require FoxP3+-expressing CD8 cells, induced by tolerogenic peptide to suppress lupus activity." (PMID 24475019, 2014). "Also, silencing of miR-21 could alter the proportion of CD4+ T cells in lupus mice." (PMID 25279261, 2014). "The objective of the study was to evaluate the proportion of CD4+CD25low/-GITR+ T lymphocytes within CD4+ T cells and compare their phenotypic and functional profile with that of CD4+CD25highGITR− T lymphocytes in systemic lupus erythematosus (SLE) patients." (PMID 25256257, 2014). "We found that Gal-9 decreased the frequency of Th1 (IFNγ+ IL-4− CD3+ CD4+ cells) significantly, while Th2 (IL-4+ IFNγ− CD3+ CD4+ cells) were unchanged in Gal-9-treated MRL/lpr lupus-prone mice." (PMID 23585851, 2013). "Further study showed that IL-17+CD4+ and IFN-γ+CD4+ T cells in lupus mice injected with ALD-DNA/MBL–treated macrophages were decreased significantly as compared with those in lupus mice injected with ALD-DNA–treated macrophages." (PMID 23626823, 2013). "In an animal model of lupus, CD70 overexpression on splenic CD4+ cells was observed in 16-week-old MRL/lpr mice with established lupus-like disease but not in their 5-week-old counterparts prior to disease development." (PMID 24000287, 2013). "FcRγ has been found in the TCR complexes of certain intraepithelial T cells, the CD4+ and CD8+ T cells of lupus patients, and human effector CD4+ T cells." (PMID 23762329, 2013). "OX40 (CD134) expression in lupus PBMCs is predominantly restricted in CD3+ CD4+ CD45RO+ T lymphocytes, and the level correlates with lupus disease activity." (PMID 24000287, 2013). "In humans, ICOS expression on CD4 and CD8+ T cells has been shown to be elevated in lupus patients, while ICOS-L (B7RP1) expression is downregulated in peripheral blood memory B cells after cognate interaction with ICOS+ T cells in coculture systems." (PMID 24000287, 2013). "Thus, in systemic autoimmune diseases, such as RA and systemic lupus erythematosus (SLE) in which CD4+ T cells play an important role, reduced number of CD4+ T cells due to HIV infection can decrease disease activity and direct a patient toward improvement." (PMID 22545055, 2012). "By positional cloning, we have determined that Pbx1 regulates the production of autoreactive CD4+ T cells and the size of the Treg compartment in the NZM2410 lupus model." (PMID 21708033, 2011).
lupus (continued). "We demonstrate that exogenous expansion and transfer of Tregs contained within the population of CD4+CD25+ T cells suppresses the onset of glomerulonephritis and prolongs survival in a murine model of lupus." (PMID 19551149, 2009). "Nevertheless, the first-degree relatives of lupus patients had reduced proportions of NKT cells and a relative shift toward increased proportions of memory and reduced proportions of naïve B and CD4+ T cells, as compared with population control individuals." (PMID 18783591, 2008). "In addition to B cells and monocytes, CXCR4 is also highly expressed on CD4+ and CD8+ T cells in both lupus patients and lupus-prone mice, where it contributes to their aberrant activation and renal infiltration." (PMID 41601976, 2026). "IL-10–producing FOXP3– (non-Treg) CD4+ T cells are expanded in lupus, including in W.Yaa mice, and the frequency of these cells was not affected by DON." (PMID 40956613, 2025). "We speculate that DHA might inhibit CD4+ T-cell function by downregulating HIF-1 signaling pathways through HIF1a (HIF1α), potentially contributing to its therapeutic effects in lupus." (PMID 40728997, 2025). "Moreover, the increased glucose metabolism of CD4+ T cell was positively correlated with SLEDAI‐2K score and cell proliferation in lupus patients with moderate and severe activity." (PMID 40801323, 2025). "We conducted co-culture experiments in which peripheral CD4+ T cells from HCs were directly incubated with senescence-like or non-senescent neutrophils from lupus patients or HCs." (PMID 40551712, 2025). "Increased thymic B cell frequency has been observed in MRL/lpr lupus-prone mice, along with increased frequencies and total numbers of CD4 SP and CD8 SP T cells, suggesting reduced negative selection." (PMID 40625741, 2025). "The study demonstrates their impact to reduced anti-dsDNA, ANA, and anti-RNP antibodies, alleviated proteinuria and disease severity, boosted CD4+ CD25+ FoxP3+ Tregs, lowered IL-6, and elevated IL-10 and TGF-β, collectively ameliorating SLE symptoms in pristane-induced lupus mice." (PMID 40534849, 2025). "We have shown that glutaminolysis is not required for Tfh cell differentiation from purified CD4+ T cells from either lupus or control mice." (PMID 40956613, 2025). "As the TC lupus-prone model, W.Yaa mice presented an expanded population of CD4+CD44+FOXP3–CXCR5+BCL6+CD162lo/–PD-1+ Tfh cells as well as follicular Tregs (CD4+CD44+FOXP3+CXCR5–BCL6–CD162lo/–PD-1+ Tfr), with a skewed Tfh/Tfr ratio, none of which were altered by DON." (PMID 40956613, 2025). "Furthermore, a direct relationship was observed between the frequencies of CD4 + and CD8 + T stem cell memory (TSCM) cells in conditions such as systemic lupus erythematosus (SLE)." (PMID 39004660, 2024). "Of note, the analysis of non-TFH CD4 + T helper cells (defined as CD45+ CD19– TCRβ+ CD8α– CD4+ CD44+ CXCR5 – cells) revealed that basophil depletion in lupus-like models impacted only the TH2 cell compartment in both mouse models." (PMID 38649353, 2024). "Indeed, studies have shown that activated CD4+ and CD8+ T cells of patients with active lupus or who are in remission for this condition express a higher level of CD154 than T cells of control individuals." (PMID 39404385, 2024). "In patients with Systemic lupus erythematosus (SLE), the levels of m5C and NSUN2 expression are decreased in CD4+ T cells, and hypermethylated m5C is involved in immune-related and inflammatory pathways, including the immune system, cytokine signaling, and interferon (IFN) signaling." (PMID 38902779, 2024). "In systemic lupus erythematosus, CD8+ T and CD4+ T cells have increased HLA-DR expression during active disease, leading to speculation that expression of HLA-DR represents an inflammatory response." (PMID 37628757, 2023).
lupus (continued). "An inflammatory environment could also promote mesenchymal stem cells’ production of lymphocyte survival cytokines, IL-7 and CXCL12, which can increase T cell recruitment and CD4+ T cell proliferation and differentiation in kidney-TLS in lupus mice." (PMID 38022566, 2023). "As in addition IL‐15‐induced circulating CD4+ T cells with cytotoxic properties were recently found in systemic lupus erythematosus, future studies of skin T cells in CLE may offer interesting insights into epigenetic potential of CD4+ TRM." (PMID 37144705, 2023). "CD4+ T cells from patients with SLE and lupus-prone mice are characterized by enhanced glycolysis." (PMID 37554724, 2023). "When lupus-prone B6.Sle1.Sle2.Sle3 (TC) mice are compared to non-autoimmune controls, both glycolysis and mitochondrial oxidative metabolism are increased in CD4+ T cells." (PMID 38137363, 2023). "CD19+ B cells and CD4+CD25− T cells were purified from the spleens of lupus mice and cocultured with or without GrB blockade." (PMID 37500293, 2023). "One recent study has shown that Nsun2 expression and m5C levels were downregulated in CD4+ T cells from patients with systemic lupus erythematosus (SLE), however, upregulated genes with hypermethylated m5C were shown to disrupt immune system and promote the flares and remission of SLE patients." (PMID 36792629, 2023). "Studies on lupus CD4+ T cells have shown that UV-B radiation inhibits SIRT1-mRNA and protein expression by activating AhR and suppressing DNMT1 activity in CD4+ T cells by binding upstream of the SIRT1 promoter translation initiation site, thus mitigating the progression of the pathological process." (PMID 37483618, 2023). "This suggests that reduced DNA methylation in the murine lupus CD4+ T cells is likely not due to the reduced expression of Dnmt genes." (PMID 38153351, 2023). "Given the non-redundant role of CD8+ Tregs in controlling germinal center reactions by eliminating activated CD4+ T-follicular helper cells, this intrinsic absence of CD8+ Treg cells could be one of the main unknown drivers of lupus in the MRL background." (PMID 35784310, 2022). "Notably, iron overload favored the expansion of spontaneous Tfh cells and GC B cells, as well as the proinflammatory cytokine-producing CD4+ T cells, aggravating autoantibody production and disease progression of MRL/lpr lupus-prone mice." (PMID 35499082, 2022). "Among the major peripheral immune cells in lupus, the autoreactive and pro-inflammatory CD4+ T cells stimulate the differentiation, proliferation and maturation of B cells to enhance the production of autoantibodies, playing a key role in the pathogenesis and progression of SLE." (PMID 36046235, 2022). "Given the extended dysregulation of Helios expression to other pivotal T-cell subsets in lupus, such as CD4+ Tregs, Tconvs, DN, and γδ T cells, Helios expression may be a good candidate as a new and versatile marker for patients with SLE and perhaps for other autoimmune pathologies." (PMID 35784310, 2022). "Infection with Epstein–Barr virus (EBV) correlates with the development of systemic lupus erythematosus (SLE) and MS, as SLE and MS patients display higher seroprevalence of EBV compared to healthy controls and some autoreactive CD4+ T cell clones can cross-react with EBV peptides." (PMID 35113966, 2022). "Remarkably, only lupus patients but not psoriasis patients or NCs had high AIM2 expression among infiltrating CD4+ T cells in skin lesions, which suggested highly expressed AIM2 may contribute to lupus pathology." (PMID 35343082, 2022). "We demonstrated that IL-39 could play a pathogenic immune role by increasing the proportion of Th2 cells and secretion of TNF-α in CD4+ and CD8+T cells in scleroderma-like and lupus-like cGVHD models." (PMID 35655245, 2022). "For example, anti-CD4 and anti-CD2-coated poly(lactic-co-glycolic) acid (PLGA) nanoparticles loaded with IL-2 and TGFβ expanded Treg cells in vitro and in vivo in the BDF1 lupus pre-clinical model." (PMID 34335564, 2021).